TUG1 (taurine up-regulated 1)
Diseases named in the same sentence as TUG1 in open-access papers (continued):
Sharing a sentence is not in itself a finding about the gene and the disease.
osteosarcoma (continued). "It was found that TUG1 could function as ceRNA to specifically sponging microRNAs to regulate gene expression and was involved in oncogenesis and development of many malignant tumors, such as gastric cancer, osteosarcoma." (PMID 35645836, 2022). "The elevated TUG1 expression indicates a poor clinical prognosis in patients with osteosarcoma, and may be a biomarker for the evaluation of the prognosis of patients with osteosarcoma." (PMID 34128849, 2021). "However, the specific mechanism of action of TUG1 in the pathogenesis of osteosarcoma and its correlation with clinical prognosis still need to be further clarified and verified by further basic studies through more large-sample and high-quality clinical trials." (PMID 34128849, 2021). "Likewise, TUG1 could impede osteosarcoma cells proliferation, migration, and invasion by miR-140-5p/PFN2 axis." (PMID 33639865, 2021). "In addition, lncRNAs TUG1, an important regulator of cancers, could facilitate proliferation and suppressed apoptosis by regulating miR-132-3p in osteosarcoma cells." (PMID 33176720, 2020). "Additionally, TUG1 silencing inhibits proliferation and induces apoptosis in cells derived from bladder cancer, osteosarcoma, hepatic, renal, colon, and gastric cancer; it is also associated with migration, invasion, tumorigenicity, the cell cycle, and angiogenesis in many other tumor types." (PMID 29657297, 2017). "Significantly reduced serum miR-425-5p expression makes it a potential prognostic marker in osteosarcoma, and when overexpressed it decreases the expression of very well-known oncogenic lncRNA MALAT1 and TUG1 in addition to suppressed tumor growth in-vivo." (PMID 35755302, 2022). "It has been reported that polydatin inhibits osteosarcoma cell proliferation and reduces DOX-resistance via TUG1 downregulation." (PMID 34425750, 2021). "The differential expression of TUG1 in osteosarcoma was analyzed by using UALCAN database, and the survival of TUG1 was analyzed as well." (PMID 34128849, 2021). "lncRNA TUG1 knockout can induce apoptosis by inhibiting MET/Akt signalling, thus reducing the resistance of osteosarcoma cells to cisplatin." (PMID 34039257, 2021). "TUG1 also boosts the level of HIF-1α by sponging miR-143-5p, thus driving the invasion, peritoneal spreading, and metastasis of osteosarcoma." (PMID 34298879, 2021). "TUG1 was significantly overexpressed in CRC patients, functioned as an oncogene in osteosarcoma by competitive binding with miR-335-5p." (PMID 34497755, 2021). "Since polydatin treatment in TUG1-silenced cells decreases AKT phosphorylation, inhibition of TUG1/AKT axis is required for its regulation of DOX-resistance in osteosarcoma cells." (PMID 34425750, 2021). "Their high expression predicted poor prognosis of osteosarcoma (MALAT1 (HR = 2.15, 95%CI: 1.67–2.76, P < 0.001), TUG1 ((HR = 2.41, 95%CI: 1.42–4.07, P = 0.001), XIST (HR = 1.79, 95%CI: 1.40–2.30, P < 0.001), NEAT1 (HR = 1.96, 95%CI: 1.05–3.68, P = 0.035))." (PMID 33639865, 2021). "These included lncRNAs TUG1, HOTAIR and UCA1 which were slightly elevated in lung metastatic osteosarcomas." (PMID 32728178, 2020). "For example, lncRNA TUG1 interacts with miR-212-3p to enhance cell proliferation and restrain apoptosis by regulating FOXA1 in osteosarcoma." (PMID 32432654, 2020). "For example, nine lncRNAs (91H, FGFR3-AS1, BCAR4, TUG1, UCA1, HIF2PUT, HOTTIP, HULC, and MALAT-1) are up-regulated in osteosarcoma, which is considered oncogenic for osteosarcoma." (PMID 31850493, 2020). "As with HULC and TUG1, lncRNA Activated by transforming growth factor-beta (lncRNA-ATB) is involved in osteosarcoma pathogenesis via regulation of a miRNA." (PMID 29657304, 2018). "Nine different long non-coding RNAs were studied in these 10 included articles, with 7 lncRNAs including MALAT1, BCAR4, FGFR3-AS1, HOTAIR, TUG1, FOXC2-AS1 and PVT1 were up-regulated in osteosarcoma cells or patients." (PMID 29245999, 2017).
osteosarcoma (continued). "The altered lncRNA expression profile possessed a total of 9 individuals, yet 7 of them (TUG1, 91H, HULC, BANCR, FGFR3-AS1, HOTTIP, and OMRUL) were overexpressed in osteosarcoma tissues/plasma, and 2 (MEG3 and TUSC7) were down-regulated." (PMID 28415638, 2017). "Recently, a great number of studies indicate that lncRNA TUG1 might participate in progression of a variety of cancers, including non-small cell lung cancer, colorectal cancer, esophageal squamous cell carcinoma, gastric cancer and hepatocellular carcinoma as well as osteosarcoma." (PMID 29245996, 2017). "Till now, the prognostic roles of multi-types of lncRNAs have been investigated in osteosarcoma as well, consisting of HULC, HOTTIP, MEG3, TUSC7, TUG1, 91H, and OMRUL, etc." (PMID 28415638, 2017). "In addition, the activation of the AKT pathway promoted the expression of lncRNA TUG1 by up-regulating the expression of FOXM1, forming a positive feedback loop in osteosarcoma." (PMID 34039257, 2021). "Taurine up‐regulated gene 1 (TUG1) was initially identified as a transcript up‐regulated by taurine, whose aberrant expression has been found in several cancers, including non‐small cell lung cancer, bladder cancer and osteosarcoma." (PMID 32597038, 2020). "The group of Li demonstrated that ectopic expression of Forkhead Box M1 (FOXM1) led to upregulation of TUG1 in osteosarcoma cell lines while a mutant form of FOXM1 did not influence TUG1 levels." (PMID 31973032, 2020). "Recently, accumulating evidence has shown that TUG1 is a negative prognostic factor for osteosarcoma patient survival, and high expression of TUG1 in patients has been correlated with enhanced bladder and esophagus cancer cells proliferation and metastasis." (PMID 28069000, 2017). "The expression levels of taurine upregulated gene 1 (TUG1) were significantly higher in human osteosarcoma tissue compared with matched non-tumorous tissue." (PMID 28353666, 2017). "There was also a positive and negative feedback regulation mode for lncRNA TUG1 in osteosarcoma." (PMID 34039257, 2021). "Among the altered lncRNA profiles, 7 lncRNAs involved TUG1, 91H, HULC, BANCR, FGFR3-AS1, HOTTIP and OMRUL, were notably increased in patients with osteosarcoma and strongly correlated to worse clinical outcomes, indicating that such lncRNAs may play oncogenic roles in maintaining tumor progression." (PMID 28415638, 2017). "However, patients with elder age, larger tumor size and distant metastasis were accompanied by overexpression of TUG1 and XIST, which further demonstrated the negative role of lncRNA TUG1 and XIST in osteosarcoma progression." (PMID 33639865, 2021).
glioma (69 papers, 2015 to 2025). A benign or malignant brain and spinal cord tumor that arises from glial cells (astrocytes, oligodendrocytes, ependymal cells). "All these results show the importance of TUG1 and associated miRNAs in glioma formation and progression processes." (PMID 30583549, 2018). "A more recent study investigated the m6A profile of TUG1 in two glioma stem cell lines and identified nine m6A peaks across the gene." (PMID 40779635, 2025). "In glioma, the lncRNA TUG1 undermines the antiglioma efficacy of dihydroartemisinin (DHA) by suppressing ferroptosis through the MAZ/FTH1 axis." (PMID 39267831, 2024). "For instance, the study conducted by Katsushima and his group on lncRNA TUG1 used antisense oligonucleotides delivered via drug delivery vehicles to target TUG1 in an in-vivo glioma model to repress glioma stem cells growth." (PMID 38059120, 2024). "Similar to findings in the present study, others have also reported downregulated lncRNA TUG1 expression in glioma and non-small-cell lung cancer." (PMID 36901763, 2023). "In high-grade gliomas, the high expression of taurine-upregulated gene 1 (TUG1) lncRNA has been reported to favor angiogenesis by inhibiting the function of miR-299, which has a binding site for vascular endothelial growth factor (VEGF)." (PMID 37444408, 2023). "In line with cancer chemoresistance, high expression of TUG1 lncRNA decreased temozolomide resistance of glioma cells by inhibiting the CSC-like properties." (PMID 37958880, 2023). "Recent studies support that targeting specific oncogenic lncRNAs by ASOs, like targeting TUG1 in glioma or LINC02273 in breast cancer, have significant therapeutic value." (PMID 35279145, 2022). "In glioma, TUG1 functions as a tumor suppressor by promoting cell apoptosis via activating caspase-3 and caspase-9 mediated intrinsic pathways and inhibiting Bcl-2 mediated anti-apoptotic pathways." (PMID 35601497, 2022). "TUG1 has been confirmed to be involved in angiogenesis, proliferation, apoptosis, migration, and invasion of glioma." (PMID 36164395, 2022). "For instance, lncRNA TUG1 acts as an oncogene in hepatocellular carcinoma via promotion of cell growth; however, TUG1 acts as a tumor suppressor in human glioma by inducing cell apoptosis." (PMID 35210436, 2022). "After construction of TUG1-overexpressed U87 and U251 glioma cells, as expected, the expression of MAZ and FTH1 at the protein level was significantly downregulated." (PMID 36164395, 2022). "The results showed that TUG1 overexpression can increase the mortality of DHA treated glioma cells, which can be reversed by MAZ overexpression, confirming the resistant mechanism by this pathway." (PMID 36164395, 2022). "For example, TUG1 can promote tumor cell apoptosis and inhibit the growth of glioma by activating caspase 3- and caspase 9-mediated proapoptosis, inhibiting bcl-2 mediated antiapoptosis." (PMID 33747256, 2021). "For example, a study showed that using ASOs targeting TUG1 coupled with a drug delivery system induced glioma cell differentiation and repressed tumor growth in vivo." (PMID 34316694, 2021). "A study showed that the lncRNA TUG1 responded to Notch signaling and promoted the self-renewal of glioma cells and that using ASOs targeting TUG1 coupled with a drug delivery system induced glioma cell differentiation and repressed tumor growth in vivo." (PMID 34316694, 2021). "Previous reports have demonstrated that lncRNA taurine upregulated gene 1 (TUG1) is dysregulated in hepatocellular carcinoma, glioma and prostate cancer." (PMID 34030715, 2021). "lncRNA taurine upregulated gene 1 (TUG1) is a direct target gene of Notch that maintains the glioma CSC phenotype manifested as high expression of CD15, Sox2, and Myc genes and an increase in neurosphere formation." (PMID 33728560, 2021).
glioma (continued). "TUG1 is also downregulated in glioma tissues, which negatively correlates with WHO tumor grade, tumor size, and patient survival, and suppresses miR-26a, which is particularly amplified in high-grade glioma tissue." (PMID 32650527, 2020). "Systemically administered TUG1-targeted ASO (asTUG1)/uPIC appreciably reduced the expression of TUG1 (>90%) in the glioma tissue compared with a Luc-targeted ASO(asLuc)/uPIC control." (PMID 31019193, 2019). "In the present study, a long non-coding RNA, TUG1, was selected as a target molecule because TUG1 silencing can suppress the self-renewal of glioma cells, potently repressing glioma cell growth." (PMID 31019193, 2019). "Using U251 and SHG-44 glioma cell lines, it was shown that TUG1 regulates PTEN expression by sponging miR-26a." (PMID 30583549, 2018). "Serving as ceRNAs for miR-144 in GECs and miR-299 in GSCs, TUG1 is able to modulate blood-tumor barrier and enhance glioma-induced angiogenesis, respectively." (PMID 30116729, 2018). "The upregulation of TUG1 has been demonstrated in several types of cancers, such as gastric cancer and glioma." (PMID 30595764, 2018). "Recent investigations have reported that in human glioma cell lines, TUG1 is down-regulated, in response to necrosis induced by a high dose of DOX." (PMID 28293170, 2017). "Recent studies have reported that Notch-directed TUG1 acts as an epigenetic modulator that regulates the glioma cancer stem cell population." (PMID 28872613, 2017). "For instance, TUG1 maintains stemness features of glioma stem cells via sponging miR-145 to promote SOX2 and MYC expression." (PMID 28983240, 2017). "For instance, TUG1 expression is induced by Notch signaling in glioma stem cells, and suppresses neuronal differentiation-associated genes by binding to the polycomb repressive complex 2 (PRC2)." (PMID 29371936, 2017). "Here, the authors show that Notch1 activation in glioma stem cells induces expression of the lncRNA TUG1, which promotes self-renewal through the repression of differentiation genes, and that targeting TUG1 represses glioma growth in vivo." (PMID 27922002, 2016). "Here, we show that TUG1, the expression of which is regulated by the Notch signalling pathway, was highly expressed in GSCs and maintained the stemness features of glioma cells." (PMID 27922002, 2016). "The long non-coding RNA TUG1 is up-regulated in hepatocellular carcinoma and promotes cell growth, but TUG1 acts as a tumour suppressor in human glioma by promoting cell apoptosis." (PMID 27733185, 2016). "Quantitative real-time PCR analysis was applied to detect the expression of lncRNA TUG1 in glioma vascular EC captured from low and high grade glioma tissues as well as in EC captured from normal brain." (PMID 26078353, 2015). "In the present study, we observed that lncRNA TUG1 was highly expressed in glioma vascular endothelial cells from glioma tissues and glioma co-cultured ECs from in vitro BTB model." (PMID 26078353, 2015). "Our research provided evidence that the expression of TUG1 was up-regulated in human glioma vascular endothelial cells and glioma co-cultured ECs from in vitro BTB model." (PMID 26078353, 2015). "LncRNA TUG1 (taurine upregulated gene 1) was highly expressed in glioma vascular endothelial cells from glioma tissues." (PMID 26078353, 2015). "ISH analysis showed that TUG1 was more strongly stained in glioma tissues than normal brain tissues." (PMID 26078353, 2015). "The expression of TUG1 was significantly increased in low or high-grade glioma group compared with that in the normal brain tissue group (P < 0.01)." (PMID 26078353, 2015). "After BTB models were established, quantitative real-time PCR analysis showed that the expression of TUG1 in GEC (glioma co-cultured endothelial cells) was significantly up-regulated compared to EC (endothelial cells obtained from BBB model) (P < 0.05)." (PMID 26078353, 2015).
glioma (continued). "TUG1 was intensively stained in the cytoplasm of glioma cell, endothelial cell and vessel lumen of glioma tissues." (PMID 26078353, 2015). "The relative mean optical densities of TUG1 was significantly increased in low or high-grade glioma group compared with that in the normal brain tissue group (P < 0.01)." (PMID 26078353, 2015). "In Situ Hybridizations (ISH) analysis was applied to detect the expression of lncRNA TUG1 in low and high grade glioma tissues as well as in normal brain tissues." (PMID 26078353, 2015). "In addition, an ASO targeting long non-coding RNA TUG1 inhibit the progression of glioma significantly." (PMID 38184597, 2024). "Indeed, the TUG1 lncRNA does just that, as it acts as a scaffold for PRC2 and YY1 to repress YY1-target genes associated with neuronal differentiation in glioma." (PMID 37444543, 2023). "In addition, lncrnas such as CCAT1 and TUG1 also play a role in promoting tumor growth and metastasis in glioma." (PMID 37228500, 2023). "Increased expression of LINC00473 in HNSCC; LINC00114, MINCR and PVT1 in NPC; Linc-RA1 in glioma; LINC00473and CYTOR in NSCLC; NEAT1 and LINC00958 in cervical cancer; H19 in cardiac cancer; LINC02582 in breast cancer; and TUG1 in bladder cancer were associated with radioresistance." (PMID 36323697, 2022). "Furthermore, TUG1 can sequester micro RNAs (miR) in the cytoplasm, e.g. miR-145 in gliomas, further implementing a role in (epi-) transcriptomic regulation." (PMID 36173935, 2022). "In addition, TUG1 overexpression also weakened the inhibitory effect of DFO on ferroptosis in DHA treated glioma cells." (PMID 36164395, 2022). "Thus, here we checked m6A modifications of previously reported glioma associated lncRNAs: MALAT1, NEAT1, XIST1, TUG1, CRNDE, LINC00461, and HOTTIP." (PMID 35361860, 2022). "Moreover, several investigations found that TUG1 had a higher expression in glioma and promoted tumor proliferation, invasion, stemness, and angiogenesis." (PMID 34322395, 2021). "In gliomas, TUG1 promotes locus-specific methylation of histone H3K27 via YY1 binding." (PMID 34316694, 2021). "Direct lncRNA TUG1 promoted the proliferation and invasion of glioma cells, and promoted apoptosis." (PMID 34039257, 2021). "They deleted taurine upregulated gene 1(TUG1) in human glioma specimens." (PMID 32276343, 2020). "LncRNA TUG1 was downregulated in glioma tissues and cells and inhibited cell proliferation and invasion by targeting miRNA-145 in regulating glioma cell self-renewal, sponging miRNA-299 in promoting angiogenesis, and interacting with miR-144 in modulating blood–tumor barrier permeability." (PMID 33817241, 2020). "Similarly, lncRNA TUG1 reinforces the self-renewal and tumorigenicity of glioma stem cells (GSCs) by two diverse molecular mechanisms." (PMID 32932969, 2020). "TUG1 maintains the stemness of glioma stem cells by acting as a molecular sponge of miR-145." (PMID 31186064, 2019). "TUG1 could promote cell proliferation, and is up-regulated in many tumor cells, including glioma, small cell lung cancer, and hepatocellular carcinoma." (PMID 30287503, 2018). "TUG1 was also found to be highly expressed in glioma endothelial cells (GECs)." (PMID 30116729, 2018). "Overexpression of TUG1 induces apoptosis in glioma cells by activating apoptotic genes caspase-3 and -9-mediated intrinsic pathways and inhibiting anti-apoptotic gene Bcl2-mediated anti-apoptotic pathways, suggesting a tumor suppressor role for TUG1 in human glioma." (PMID 28187439, 2017). "The role of TUG1 in glioma pathogenesis was recently identified by several studies." (PMID 28187439, 2017). "TUG1 is upregulated in CSCs of gliomas and downregulated upon inhibition of Notch." (PMID 28872613, 2017).